CXCR4 (C-X-C motif chemokine receptor 4)
Diseases named in the same sentence as CXCR4 in open-access papers (continued):
Sharing a sentence is not in itself a finding about the gene and the disease.
cancer (continued). "In our previous report, we have studied the CTCs in HCC and shown that CD90+CXCR4+ HCC cells may be CTCs and selective elimination of these cells may substantially improve the current HCC therapy by reducing cancer metastasis." (PMID 30844765, 2019). "Both CXCR4 and SDF-1 were expressed in the cancer cells themselves." (PMID 31744214, 2019). "CXCR4 was also expressed in both ED-type and EX-type cancer parenchyma; however, CXCR4 was not expressed in the non-cancerous epithelium adjacent to the cancer parenchyma, similar to PTCH expression." (PMID 31744214, 2019). "Previous studies of CXCR4 in OSCC have focused on CXCR4 expressed on cancer cells and have not reported CXCR4-positive blood vessels in OSCC." (PMID 31336612, 2019). "In addition, knockout of TIPE2 resulted in the downregulation of CXCR-4 and MMP-9, which are involved in the invasion, migration, and metastasis of cancer cells." (PMID 31817720, 2019). "Mechanistically our study suggests that by increasing the expression of chemokine receptors, CXCR4 and CCR5, decreased RhoA expression increases the proclivity of cancer cells for the sentinel lymph node and enables the cancer cells to have access to the circulation and metastasize." (PMID 31705019, 2019). "Cancer cells isolated by the sphere formation assay displayed self‐renewal properties, upregulation of EMT markers (vimentin, Snail/Slug and N‐cadherin), stemness and developmental genes (CD105, CD133, CXCR4, NANOG, MYCN, and WNT)." (PMID 30883740, 2019). "Despite the fact that OSCC cells express a considerably high level of CXCR4, neither proliferation nor survival of the cancer cells was inhibited by CXCR4 antagonists." (PMID 31336612, 2019). "Analyses of transcripts altered in TMED3 kd cells over control levels revealed a group of 63 RNAs enhanced twofold or more that included several genes previously shown to promote pro-metastatic behavior in different cancers, including SOX8, ASCL2, FGF19, and CXCR4." (PMID 31253868, 2019). "Besides presence in circulation, CTCs are identified with a number of surface markers, among which CXCR4, the receptor for stromal cell -derived factor-1 (SDF-1), is the best characterized one in different types of cancer." (PMID 30844765, 2019). "The role of CXCL12/CXCR4 on chemotaxis has been reported in various tumors, as shown by the high levels of CXCL12 in bone, lymph nodes and lung which can attract CXCR4-expressing cancer cells 42-45." (PMID 31534521, 2019). "Of these genes, CXCL12, a chemokine and its cell surface receptor, CXCR4, and CXCR2 which are known to be involved in cancer cell proliferation and metastasis were verified by qRT-PCR to be significantly increased by ~3-fold in the HCC97L cells transfected with the CPE-ΔN expression plasmids." (PMID 31798768, 2019). "While standard diagnostics could only diagnose a cancer of unknown primary, the use of [68Ga]-Pentixafor-PET/CT (CXCR4-PET/CT, a radiotracer targeting CXCR4) and a liquid biopsy of the cerebrospinal fluid revealed the primary NSCLC." (PMID 29721166, 2018). "CXCR4 expression levels are generally low or absent in most healthy tissues; however, in cancer, CXCR4 was found to be overexpressed in a variety of cancers over 23 types of cancer." (PMID 29959873, 2018). "Combined, these data suggest that SDF-1 directed chemotaxis to certain microenvironmental stem cell niches is a general phenomenon of CXCR4-expressing hematopoietic and non-hematopoietic cancer cells." (PMID 30622535, 2018). "It is also reported that ALDH1, CXCR4, and CD133 are well-known markers of highly aggressive, drug-resistant, invasive, and cancer stem cell phenotypes, suggesting that our KU-CSLCs are highly aggressive and drug-resistant cancer stem cell-like cells." (PMID 29747452, 2018).
cancer (continued). "CXCR4, however, is expressed on immune cells suggesting that SDF-1/CXCR4-targeted anti-cancer therapy at the same time interferes with the immune response to cancers and cancer cells in e.g., circulation or micrometastases." (PMID 30622535, 2018). "The chemotactic properties of CXCR4 combined with its ability to activate pro-survival mechanisms and stimulate cellular proliferation places the CXCR4/CXCL12 axis at the vanguard of metastasis and tumorigenesis for many cancers." (PMID 29682200, 2018). "Here, we aim to study the contribution of CXCR4 and CXCR7 in modulating CSC properties in cancer." (PMID 29460395, 2018). "In addition, we demonstrated that the overexpression or knockdown of KRT19 regulated cancer stem cell reprogramming by modulating the expression of cancer stem cell markers (ALDH1, CXCR4, and CD133) as well as the level of p-Src and p-GSK3β (Tyr216)." (PMID 29747452, 2018). "WEV+NP showed greater activities than WEV alone in decreasing the surface expression of the chemokine receptors CXCR3, CXCR4 and CXCR6 and decreased migration of the cancer cells, suggesting this approach possesses the promising therapeutic potential for clinical application of snake venoms." (PMID 30158426, 2018). "The wound healing assay shows that the delivered CXCR4 siRNA significantly suppresses the wound closure, suggesting that silencing CXCR4 effectively inhibits cell migration, which is consistent with the findings that CXCL12/CXCR4 signaling enhances the migration and invasion of cancer cells." (PMID 30242189, 2018). "On the other hand, it was shown that both CXCR4 and CXCR7 responded to CXCL12 to greatly increase human lymphoma cells’ migration, indicating that CXCR7 might be an efficient target for cancer treatment." (PMID 29977203, 2018). "In fact, it has been reported in the literature that cells in growing cancer cell lines may express markers, such as CD133 and CXCR4, that are highly expressed in normal hematopoietic and non-hematopoietic stem cells." (PMID 30375490, 2018). "Despite its over-expression in many cancer cell lines, the data presented suggests that ACKR3 does not have a role in chemotaxis but its presence can increase cell front velocity if co-expressed with CXCR4." (PMID 30441765, 2018). "These modulations may be partially due to the alteration of cancer stem cell markers (ALDH1, CXCR4, and CD133) expression as well as the phosphorylation of Src and GSK3β (Tyr216)." (PMID 29747452, 2018). "Furthermore, this study provides the field with a molecular tool set of differing CXCR4 antagonists to study receptor and cellular behavior as it applies to immune system regulation, HIV infection, and cancer pathology." (PMID 29682200, 2018). "In this study, we hypothesized that miRNAs might be an important mediator in the progression of cancer, such as invasion, metastasis and chemoresistance, in response to the activation of CXCL12/CXCR4 axis." (PMID 28176874, 2017). "Here, we demonstrated that CXCR4-expressing PTC cells were able to follow CXCL12-expressing senescent thyrocytes, and that CXCL12-expressing senescent thyrocytes effectively attracted CXCR4-expressing cancer cells in the migration assay." (PMID 28489070, 2017). "CXCR4 is usually overexpressed in a variety of human cancers, but absent or low in a lot of normal tissues." (PMID 28403883, 2017). "Blocking CXCR4 and/or CXCL16 neutralization, alone or in combination, resulted in significant inhibition of patient-derived cancer cells migration to brain metastatic CAF aggregates, further supporting the importance of CXCL16 and CXCL12 in migration of CTCs into brain-associated microenvironment." (PMID 28649646, 2017). "CXCR4 and CXCR7 are involved in various forms of cancer and their metastasis." (PMID 28945785, 2017).
cancer (continued). "Moreover, blocking of CXCR4, the chemokine receptor for CXCL12, and neutralization of CXCL16, the ligand for CXCR6 in patient-specific cancer cells significantly prevented the migration of cancer cells to the tumor microenvironment (TME)." (PMID 28649646, 2017). "This is because using a cytotoxic agent and CXCR4-KLA together could simultaneously eliminate both chemo-sensitive and drug–resistant cancer cells." (PMID 28196146, 2017). "The comparatively high frequencies for some cancers did not bear a simple relationship to the site of metastasis, since most metastases were to lymph nodes for both the metastases that were CXCR4+ and those that were CXCR4-." (PMID 29088715, 2017). "On cancer cells, it binds to and signals via CXC chemokine receptors type 4 (CXCR4) and 7 (CXCR7)." (PMID 29112161, 2017). "Agents that target CXCR4, including small molecule inhibitors, monoclonal antibodies (mAbs), and peptide antagonists, have been shown to disrupt SDF-1/CXCR4 binding and downstream signaling with therapeutic applications in cancer and immunopathology." (PMID 29212254, 2017). "CXCR4 and its ligand, CXCL12, can promote metastasis by preventing anoikis in cancer cells." (PMID 28489070, 2017). "Despite the large number of studies on ferritin and particularly on its heavy subunit in neoplastic cells, the role of FHC in CXCR4 signalling in cancer has not been addressed so far." (PMID 28774348, 2017). "Nonetheless, the data do not suggest that CXCL12 was unavailable for activating CXCR4 on the cancer cells." (PMID 29088715, 2017). "However, CXCR4 and its natural ligand stromal derived factor-1α (CXCL12) also play a crucial role in the development, proliferation, and metastasis of cancer." (PMID 27896627, 2017). "To investigate whether activation of CXCL12/CXCR4 axis promotes EMT, we performed the assays of RT-PCR and Western blot to determine the expressions of E-cadherin and vimentin in cancer cells." (PMID 28176874, 2017). "CXCR4 promotes metastasis by activating activating extracellular signal-regulated kinase 1/2 (ERK1/2), Akt/PKB and Nuclear factor-κB (NF-κB), which increases the adhesion and invasive ability of cancer cells in part by the activity of MMP2 and MMP9." (PMID 28191313, 2017). "In contrast to CXCR4, CXCR7 is expressed on embryonic HSCs and cancer transformed cells." (PMID 27092040, 2016). "Information available in this area will aid not only in understanding how cancer cells may escape HMGA1 or CXCR4 targeted therapies but will also provide a rationale for combinatorial therapies targeting both HMGA1 and CXCR4." (PMID 27602961, 2016). "Indeed, we showed that some of the cancer stem cell populations upregulated in vivo in spheroid-plug model tumors are already induced by in vitro spheroid culture (CXCR4+CD49f− in LLC and CXCR4+CD49f+ in B16)." (PMID 26385771, 2016). "For cancer cells, the chemotaxis response following CXCL12 binding to CXCR4 was abolished, inhibiting CXCR4-mediated cell migration, if the receptor homodimerization was modulated by removing cholesterol or blocked by a TM4 peptide (an analog of the transmembrane (TM) helix 4 of CXCR4)." (PMID 27812115, 2016). "Therefore, the CXCR4 and SDF-1 axis offers a therapeutic opportunity for anti-cancer drug development." (PMID 26954567, 2016). "From these results, we established CXCR4, CXCL1 and HMGCS1, the intersecting genes of the datasets with high connectivity and p-value of < 0.05, as significant genes in the identification of cancer stem cells." (PMID 26870956, 2016). "While it was reported that CXCR4 may be expressed on both lymphocytes and cancer cells, we found that 4T1 TDLN B cells expressed CXCR4." (PMID 27528023, 2016). "The SDF-1α/CXCR4 biological axis can activate multiple intracellular signaling pathways, including the FAK, AKT, ERK1/2, P38, STAT3, mTOR, and Wnt/β-catenin signaling pathways in various cancers." (PMID 25609203, 2015).
cancer (continued). "Therefore, as CXCR4 is overexpressed in several human cancers, the blockade of CXCR4–CXCL12 interaction has been extensively investigated as a potential cancer therapeutic." (PMID 26030674, 2015). "Two new ligands, the ubiquitin and the macrophage migration inhibitory factor were recently discovered to bind CXCR4, however their role in cancer biology has not been documented as much as SDF-1α." (PMID 26231656, 2015). "In addition, IL-1β induced the activation of extracellular signal regulated kinase (ERK) and ERK inhibition decreased the up-regulation of CXCR4 induced by IL-1β, suggesting the involvement of ERK signaling in cancer metastasis." (PMID 26176534, 2015). "In contrast, knockdown of CXCR4 in HCC cells abrogated the anti-apoptotic function of CAFs, which further confirmed that the SDF-1/CXCR4 pathway plays an essential role in the repression of cancer apoptosis mediated by CAFs in the HCC microenvironment." (PMID 25909286, 2015). "Curiously, higher CXCR4 expression in intratumoral fibroblasts was positively correlated with survival rates of patients, and both CXCL12 and CXCR4 expressions were correlated in cancer cells, intratumoral fibroblasts, and endothelial cells." (PMID 26161302, 2015). "Via CXCR4, MIF has been shown to recruit many cell types, including T-cells, B-cells, eosinophils, endothelial progenitor cells, mesenchymal stromal cells, as well as cancer cells." (PMID 26347749, 2015). "Pooled analysis shows that CXCR4 over-expression is significantly associated with poorer PFS (HR 2.04; 95% CI, 1.72-2.42) and OS (HR=1.94; 95% CI, 1.71-2.20) irrespective of cancer types." (PMID 25669980, 2015). "Therefore, the CXCR4/SDF-1 axis represents a highly relevant molecular target in MM and other cancers due to its important role in pathogenesis and its potential involvement as a mediator of resistance to treatment." (PMID 25736399, 2015). "In addition the partial inhibition of the CHG exposed PSC/CCM induced cancer cell proliferation by AMD3100, a specific CXCR4 blocker strongly refers to the functional role of the CXCL12-CXCR4 binding." (PMID 26010611, 2015). "The cancer related category apoptosis was over-represented with both up- and down-regulated genes, represented by two up-regulated genes (TNS3, EMP1) and five genes down-regulated (DNASE1L2, CXCR4, Gal-7, FKBP5, SGK1)." (PMID 25867603, 2015). "Both uPAR and CXCR4 expression is strongly up-regulated and represents a negative prognostic factor in various cancers, including haematological malignancies 11,19,20." (PMID 26082201, 2015). "Moreover, inhibition of the CXCR4 pathway by AMD3100 significantly decreased the colonization of the fluorescent cells in these organs, indicating that radiation-induced cancer cell colonization is mediated by SDF-1α/CXCR4." (PMID 25843954, 2015). "To explore the novel role of the CXCL12/CXCR4 axis in PNI, we evaluated the representative immunohistochemical staining properties of CXCR4 and CXCL12 in the resected PCa specimens accompanied by PNI, where the staining of S100 served as a nerve tissue marker and CK19 served as a cancer cell marker." (PMID 25605248, 2015). "Because of the small sample sizes of these five types of cancers, meaningful analysis of the role of CXCR4 on outcome in patients with these cancers were not possible." (PMID 25669980, 2015). "Regarding the stemness and the dissemination potential, cancer stem cell and metastatic cells share comparable behaviour and properties such as the capacity for self-renewal, the requirement for a specific microenvironment to grow and the SDF1/CXCR4 axis." (PMID 26528758, 2015). "In addition to assisting in the dissemination of CRC, CXCR4 has also been shown to support growth of metastases through its co-expression with glycoprotein CD133, a marker of cancer stem cells." (PMID 26552750, 2015).
cancer (continued). "Next, going out of the microarray data analysis, we shifted our attention to upstream regions of CXCR4 (chemokine (C-X-C motif) receptor 4 gene) and CXCR7 (chemokine (C-X-C motif) receptor 7 gene), as both are expressed in many types of cancer and have an important role in metastasis." (PMID 26016667, 2015). "Therefore, it is very important to search for appropriate SDF-1signalling pathways through CXCR (both CXCR4 and CXCR7) in different cancers that would suggestnew therapeutic strategies." (PMID 24416254, 2014). "The notion that CXCR4/R7 expression in cancer is, in most cases, a negative prognostic factor is well supported." (PMID 24904289, 2014). "CXCR4 selectively binds the CXC chemokine ligand-12 (CXCL12, or SDF-1), which has been found to be important in the tumorigenesis, proliferation, metastasis, and angiogenesis in cancers." (PMID 25471741, 2014). "CXCR4 and c-MYC are addictive oncoproteins of many malignant tumors." (PMID 25115391, 2014). "The invasive behavior of cancer cells might indirectly depend on locally released CXCL2 that, via an autocrine mechanism, binds to CXCR4 impairing chemotaxis towards CXCL12-producing target organs and metastatic spread." (PMID 25484899, 2014). "This is consistent with the previous report that CXCR4 could influence EMT formation and cancer invasion." (PMID 25471741, 2014). "Asian patients with high levels of CXCR4 expression in cancer cells get remarkably poor prognosis, while non-Asians did not." (PMID 24658065, 2014). "Since CXCR4 and CXCR7 are both involved in cancer malignancy, and in particular in GBM angiogenesis, molecules able to interact and block either CXCL12 itself or both receptors simultaneously could represent an improved pharmacological approach." (PMID 24904289, 2014). "The interaction of GBM cells with the microenvironment that protects cancer cells from the chemo- and radio-therapy stress, becomes even more relevant in the context of CXCL12/CXCR4 up-regulation observed after treatment with anticancer drugs, and particularly after anti-VEGF antibodies." (PMID 24904289, 2014). "CXCR4 and its ligand CXCL12 can promote the proliferation, survival, and invasion of cancer cells." (PMID 24810923, 2014). "Subsequently, the identification of non-HIV-related functions boosted new applications of CXCR4 inhibitors such as stem cell mobilization, inflammation and cancer treatments." (PMID 24904289, 2014). "The human CXCR4 contains a nuclear localization motif and nuclear CXCR4 translocation has been reported to be a negative prognostic marker in several highly proliferative cancers." (PMID 24885150, 2014). "We measured CXCR4 and CXCR7 mRNA levels in human polyps (n = 30) and carcinomas (n = 46)." (PMID 24629239, 2014). "Strong CXCR4 expression was detected in 31.4% (48/153) of the cancer samples, whereas the remaining 105 samples displayed weak or absent CXCR4 staining." (PMID 23987636, 2013). "The present results are consistent with those of previous studies that demonstrated that CXCR4 inhibition with the non-peptide small molecule AMD3100 significantly inhibits cancer cell invasion." (PMID 24179538, 2013). "Not surprisingly, the suitability of SDF1a and CXCR4 as potential targets for anti-cancer therapeutics is the subject of on-going research." (PMID 23422038, 2013). "They found out that treatment with that chemokine enhances adhesion of cancer cells to endothelia through expression of CXCR4 on the endhothelia independent of the expression of CXCR4 or CXCR7 on the cancer cells." (PMID 24305653, 2013). "Staining for the CXCR4 protein was also identified in the cytoplasm and cell nucleus of the cancer cells, but not in the cell nucleus of the normal pancreatic cells obtained from the non-cancerous regions of the PDAC tissue." (PMID 23761820, 2013).